INTS6 (integrator complex subunit 6)
Diseases named in the same sentence as INTS6 in open-access papers (continued):
Sharing a sentence is not in itself a finding about the gene and the disease.
tumor (continued). "This suggests a mechanism in which INTS6 might be post-transcriptionally deregulated in tumor cells, either translationally or at the level of protein stability." (PMID 39001402, 2024). "Additionally, we found that the downstream target genes just like ZEB1 and MMP13, which play an important role in tumour regulation, were decreased in the INTS6 overexpressing cells." (PMID 28899352, 2017). "In addition, they also had shorter disease-free survival time with poor pathology grades II–III and tumour recurrence (p<0.001 and p = 0.001) than patients with high INTS6 expression." (PMID 28899352, 2017). "The results revealed that INTS6 expression localized primarily to the nuclei of tumour cells." (PMID 28899352, 2017). "Furthermore, the expression of INTS6 (p = 0.001), tumour size (p = 0.004), pathology grade (p = 0.009) and vascular invasion (p = 0.001) were correlated with disease-free survival." (PMID 28899352, 2017). "Furthermore, the functional studies – include growth curves, cell death, migration assays and in vivo studies – verify the tumor suppressive roles of INTS6 and INTS6P1 in HCC." (PMID 25686840, 2015). "Here, we report that INTS6 plays a critical role as a tumor suppressor in HCC." (PMID 25686840, 2015). "Disruptions in this balance, such as through mutations in INTS6 or INTS11, lead to aberrant transcriptional elongation, resistance to CDK9 inhibition, and amplified oncogenic transcriptional responses, linking the INTS complex to both transcriptional regulation and tumor susceptibility." (PMID 40966122, 2025). "Therefore, we report that INTS6 is a potential and significant potent tumour suppressor in HCC." (PMID 28899352, 2017). "Our findings demonstrated that INTS6 induction significantly suppressed HCC cell proliferation by promoting G1 phase arrest, highlighting its potential role as a tumor suppressor." (PMID 41020855, 2025). "Integrator complex subunit 6 (INTS6), a putative tumor suppressor shown to downregulate Wnt/β-catenin signaling was also depleted upon the elimination of DHX29 expression." (PMID 34552058, 2021). "Here, we are the first to report that the down-regulation of INTS6 strongly correlates with high AFP levels, poor pathology grades, and tumour recurrence." (PMID 28899352, 2017). "Correlation analyses showed that INTS6 expression was significantly correlated with serum alpha-fetoprotein levels (AFP, p =0.004), pathology grade (p =0.005), and tumour recurrence (p =0.04)." (PMID 28899352, 2017). "Patients with low INTS6 expression had shorter survival time with poor pathology grades II–III and tumour recurrence (p<0.001 and p = 0.007)." (PMID 28899352, 2017). "The current study reports, for the first time, that INTS6 and its pseudogene INTS6P1 are tumor suppressors in HCC." (PMID 25686840, 2015). "The targets of hsa-miR-146b and its viral counterpart are INTS6 and IPO, which are a tumor suppressor and a mediator of inflammation, respectively." (PMID 25544772, 2014). "However, some studies have recently revealed its involvement in tumor development, including INTS3, INTS6, INST7, and INSTS8." (PMID 37537630, 2023). "INTS6P1, a tumor suppressive pseudogene-derived lncRNA, exerted its roles in HCC by competitively binding to oncogenic miR-17-5p and thus upregulating its cognate gene INTS6." (PMID 32185172, 2020). "Therefore, HCC patients with low INTS6 expression had a higher tendency to have high AFP levels, a poor pathology grade, and tumour recurrence." (PMID 28899352, 2017). "Interestingly, the overlap of all three tumor groups included the region containing INTS6, an annotated tumor related gene (also known as DICE1, Protein deleted in cancer 1)." (PMID 20735817, 2010). "Notably, INTS6 acts as a tumor suppressor by inhibiting the Wnt/β-catenin signaling pathway, thereby impeding HCC progression, whereas INTS8 enhances EMT via activation of the TGF-β pathway, promoting tumor aggressiveness." (PMID 41020855, 2025).
tumor (continued). "However, the INTS6 gene product does not have a significant prognostic value as a biomarker for tumor progression." (PMID 39001402, 2024). "Interestingly, we found that INTS6, also known as DICE1 (deleted in cancer 1), was downregulated in several cancer types, thus corroborating previous literature data and supporting its role as a tumor suppressor gene." (PMID 28468258, 2017).
cancer (17 papers, 2009 to 2025). A tumor composed of atypical neoplastic, often pleomorphic cells that invade other tissues. "Collectively, these findings underscore the diverse roles of the individual integrator subunits in cancer biology, highlighting INTS6 as a promising therapeutic target in HCC." (PMID 41020855, 2025). "One potential explanation for the association between low INTS6 expression and malignant nature in HCC is the involvement of EMT, a biological process closely linked to cancer progression, metastasis, and therapeutic resistance." (PMID 41020855, 2025). "INTS6 was originally identified as a tumor-suppressor protein, and it is now clear that several additional INTS subunits are misregulated or mutated in human cancers." (PMID 40966122, 2025). "Furthermore, tumors in which INTS6 or INTS6P1 was up-regulated, displayed a lower cross sectional cancer component, when compared to control tumors." (PMID 25686840, 2015). "INTS6P1 (integrator complex subunit 6 pseudogene) and INTS6 (integrator complex subunit 6) functioned as ceRNAs through miR-17-5p, whilst CTNNAP1 (catenin alpha 1 pseudogene) and CTNNA1 (catenin alpha 1) competed for miR-141, leading to cancer regression in HCC and CRC, respectively." (PMID 29702599, 2018).
neurodevelopmental disorder (1 paper, 2025). A behavioral and cognitive disorder with onset during the developmental period that involves impaired or aberrant development of intellectual, motor, or social functions. "Here, we identify INTS6, a subunit of the Integrator complex, as a novel gene associated with neurodevelopmental disorders (NDDs)." (PMID 40966122, 2025). "Dysfunction of INTS6 leads to a newly neurodevelopmental disorder in humans and is associated with impaired cortical development, disrupted synaptic maturation, and behavioral deficits in mice." (PMID 40966122, 2025).
neurological disorders (1 paper, 2025). "Unlike dominant mutations in INTS6, biallelic mutations in other INTS genes, such as INTS11, are associated with neurodevelopmental or neurological disorders." (PMID 40966122, 2025).
INTS6 also shares sentences with these, for which no sentence is quoted: viral infections (4 papers); non-small cell lung carcinoma (3); cervical carcinoma (2); prostate tumor (2); acute myeloid leukemia (1); asthma (1); gastric cancer (1); infection (1); macular degeneration (1); Myelodysplasia (1); oral cancer (1); placental insufficiency (1); preeclampsia (1); rhabdomyosarcoma (1); squamous cell carcinoma (1); vaginal carcinoma (1).